IL6 (interleukin 6)
Diseases named in the same sentence as IL6 in open-access papers (continued):
Sharing a sentence is not in itself a finding about the gene and the disease.
asthma (continued). "Several pulmonary diseases including asthma, acute lung injury, COPD and acute respiratory distress syndrome (ARDS), are associated with abnormal TNF-α, IL-1β and IL-6 expression." (PMID 31395940, 2019). "A recent study revealed an IL-6 trans-signaling specific gene signature in patients with asthma, which was accompanied by an increase in submucosal T cell and macrophage infiltration." (PMID 31694340, 2019). "The present study examined the expression of proinflammatory cytokines known to be associated with inflammatory airway diseases such as asthma and COPD (IL-6, IL-8, and TNF-α mRNA) after apocynin treatment." (PMID 31612365, 2019). "The IL-6R coding SNP rs2228145 (Asp358Ala), which increases IL-6R shedding and promotes IL-6 trans-signalling is associated with lower predicted FEV1 and is more frequent in the severe asthma clusters in the Severe Asthma Research Program (SARP) cohort." (PMID 31395050, 2019). "In this study, galectin-3 secretion by MDMs was lower in participants with asthma compared with healthy participants, while IL-6 and CXCL8 secretion was similar between the groups." (PMID 30606211, 2019). "As one of the important factors that regulate asthma severity, IL-6 induces IL-4 up-regulation and stimulates Th17 cell differentiation." (PMID 31790411, 2019). "Increased SOCS3 and IL-6 expression in atopic conditions such as asthma, rhinitis, dermatitis, conjunctivitis and food allergies play pivotal role in the development of atopic conditions." (PMID 31251775, 2019). "In a mouse model of asthma, IL-6 trans-signaling rather supported Th2 cytokine production, whereas classic IL-6 signaling was needed for the development of FoxP3+ regulatory T cells in the lung." (PMID 31694340, 2019). "IL-1β and IL-6, each of which are critical to Th17 differentiation, are expressed at high levels in the inflamed airways of children with severe asthma." (PMID 31284537, 2019). "In the present study, we found evidence that pro-inflammatory cytokine responses (IL-6 and IL-8) were broader and stronger in the children with pre-existing asthma." (PMID 31703379, 2019). "Third, a potential limitation of TCZ when considered for the treatment of asthma or other allergic diseases is that it blocks both mIL‐6R and sIL‐6R,85 that is, it inhibits both IL‐6 classic signalling and trans‐signalling." (PMID 31223480, 2019). "In rat models with asthma, the treatment of NM showed a decreased eosinophil and neutrophil infiltration, and decreased levels of inflammatory factors such as IL-5, IL-6, IL-13, and IL-17 in bronchoalveolar lavage fluid." (PMID 31552177, 2019). "The anti-IL-6 antibody for granulocytic airway inflammation therapies in asthma has also been reported." (PMID 31284537, 2019). "Serum YKL-40 positively correlated with non-T2 inflammatory signatures such as IL-1β and IL-6, which predicts insensitive responses to asthma treatment." (PMID 31113430, 2019). "A role for IL‐6 signalling on asthma pathophysiology is also supported by two parallel observations from human genetic association studies." (PMID 31223480, 2019). "MDM galectin-3 secretion was lower in asthma (9.99 (2.67, 15.48) ng/mL) compared with the healthy controls (20.72 (11.28, 27.89) ng/mL; p = 0.044) while IL-6 and CXCL8 levels were similar." (PMID 30606211, 2019). "Levels of IL-6 have been shown to be elevated in a number of inflammatory diseases such as asthma and COPD." (PMID 31612365, 2019). "Our findings suggest that the role of the IL-6/IL-6R axis in asthma exacerbations warrants further investigation." (PMID 31395050, 2019). "We also found that the pro-inflammatory cytokines IL-6 and IL-8 were elevated in RV-C-infected children with asthma when compared to controls." (PMID 31703379, 2019). "The ex vivo lipopolysaccharide (LPS)-induced release of pro-inflammatory cytokines including TNF-α, IL-6, and IL-1β from asthma sputum cells was abrogated by IL-37." (PMID 29988381, 2018).
asthma (continued). "In support of this notion, IL-6, a profibrotic cytokine in asthma model was also lower in March1−/− ova-ova." (PMID 29854835, 2018). "Clinical trials of Suricumab, a fully human monoclonal antibody against IL-6, are currently in progress and therapeutic efficacy of systemic IL-6 blockade for severe asthma is yet to be determined." (PMID 30534125, 2018). "Direct in vitro evidence points to the release of some asthma-related cytokines and a prostanoid with inflammatory properties (IL-2, IL-6, PGE2) from human immune cells (including T-lymphocytes and monocytes)." (PMID 30333747, 2018). "To further investigate the role of IL-6 from dendritic cells in atopy during asthma, we analyzed systemic inflammatory response by determining IgE concentration in the serum and BAL fluid of the experimental animals." (PMID 30534125, 2018). "We subsequently focused on IL-6, CXCL8 and GM-CSF as these cytokines are well-established to be up-regulated by PM exposure, as well as being implicated in the pathogenesis of asthma, with elevated concentrations seen in lungs of asthmatic individuals." (PMID 30157189, 2018). "Asthmatic patients (including allergic and intrinsic asthma) were shown to have increased IL-6 serum and BAL fluid levels." (PMID 30380761, 2018). "A recent study in mouse model of asthma confirmed an important contribution of IL-6 produced by epithelial cells in the pathogenesis of aspergillus-induced asthma." (PMID 30534125, 2018). "In the low-dose (10 μg) HDM-induced acute asthma model, we found that cell type-restricted deletion of IL-6 in macrophages leads to significant reduction of eosinophilic inflammation in the lungs and to attenuation of Th2 accumulation in the periphery." (PMID 30534125, 2018). "Similar to other proinflammatory cytokines, IL-6 is elevated in asthma and plays an active role in this disease." (PMID 30534125, 2018). "Expression levels of TSLP, the master-regulator of airway remodeling during asthma, and of TGFβ1, which is involved in airway inflammation and hyper-responsiveness, were also decreased in IL-6 KO mice as compared to WT mice." (PMID 30534125, 2018). "More importantly, miR-221/222 has been reported to target estrogen receptor alpha (ESR1), and miR-221-3p has been shown to regulate IL-6 release from abnormal airway smooth muscle in patients with severe asthma, especially women." (PMID 29739446, 2018). "It is known also that both IL-6 and TNFα can be involved in asthma pathophysiology and allergic diseases, and allergic diseases would appear to be more frequent in OCD patients, giving weight to elevated IL-6 and TNFα levels in some OCD cases." (PMID 30096863, 2018). "Evaluation of inflammatory markers interleukin-6 (IL-6) and matrix metalloproteinase-9 (MMP-9) in serum showed higher levels in asthmatic patients vs controls and were associated with a more severe asthma." (PMID 30598830, 2018). "As pro-inflammatory cells, Th17 cells can induce the occurrence of asthma and autoimmune diseases by secreting inflammatory factors such as IL-17A, IL-17F, IL-6 and tumor necrosis factor-α." (PMID 30089474, 2018). "In contrast, mice with deficiency of IL-6 in dendritic cells demonstrated attenuated neutrophilic, but regular eosinophilic response in HDM-induced asthma." (PMID 30534125, 2018). "Exposure to air pollutants aggravates asthma symptoms and airway inflammation characterized by an increase in IL-6 and IL-8." (PMID 29882826, 2018). "A number of studies have demonstrated overexpression of IL-6 by bronchial epithelial cells in patients with asthma, both in adults and children." (PMID 30534125, 2018). "Analyzing the role of IL-6 in asthma revealed that IL-6 mRNA was constitutively present in mouse primary lung epithelial cells, but not in resident immune cells." (PMID 30380761, 2018).
asthma (continued). "Our results indicate that IL-6 from macrophages promotes Th2-driven eosinophilic inflammation during HDM-induced asthma, probably, due to IL-6-mediated macrophage polarization toward the alternatively activated macrophages." (PMID 30534125, 2018). "Circulating IL-6 is elevated in asthmatic patients and in bronchoalveolar lavage fluid of patients in whom asthma is clinically active." (PMID 29246125, 2017). "The addition of LL-37 (2 and 10 μg/ml) in eosinophil cultures did not affect the surface expression of adhesion molecules ICAM-1/CD18 or the release of asthma-related inflammatory IL-6, CXCL8 and CCL4." (PMID 28500314, 2017). "IL-1, TNF-a, and IL-6 are considered to be expressed in most types of inflammation, especially asthma." (PMID 29250125, 2017). "The increased presence of the pro-inflammatory IL6 and IL8 were previously shown to be associated with the pathophysiology of asthma." (PMID 29231896, 2017). "IL-6 high patients had significantly worse lung function and more frequent asthma exacerbations than IL-6 low patients." (PMID 29246125, 2017). "This indicates that IL-6-mediated inflammation is a major driver of increased hypercoagulability in asthma, similarly to several other diseases including atherosclerotic vascular disease." (PMID 28429138, 2017). "IL6 mRNA expression was similarly affected by the different transfection variables in ASMCs from patients with severe asthma." (PMID 27484035, 2017). "This study demonstrated that IL-4, IL-6, and IL-12 levels in PB were associated with lung function, cellular immune function, and QOL in children with moderate-to-severe asthma." (PMID 28328807, 2017). "Subsequent targeting studies demonstrated the importance of this lncRNA in controlling both proliferation and IL-6 release in ASMCs from patients with severe asthma." (PMID 27484035, 2017). "Age, asthma duration, IL-6, FeNO, and serum superoxide dismutase (SOD) levels were higher in the GCs group, compared to the ICs group (P= 0.0173, P= 0.0009, P= 0.045, P= 0.0237, and P= 0.0054, respectively)." (PMID 29849682, 2017). "The pleiotropic cytokine IL6 is viewed as a marker of airway inflammation in asthma (showed in humans and animal models) and has been proposed as a therapeutic target in clinical trials." (PMID 29231896, 2017). "In asthma, IL-6 is upregulated in pulmonary epithelial cells by various stimuli and is involved in facilitating IL-4 differentiation, downregulating Th2 cell differentiation, and promoting Th17 cell differentiation." (PMID 29151835, 2017). "IL-6, C-reactive protein (CRP) and other inflammatory markers are associated with asthma and eczema." (PMID 27476619, 2017). "For example, mast cells are major producers of VEGF and IL-6, both of which having the potential to contribute significantly to the pathology of inflammatory disorders, e.g., asthma." (PMID 29230220, 2017). "Both IL-6 and IL-13 levels are usually elevated in asthma patients and are presumed to be closely correlated; we found that IL-6 levels were similar to IL-13 levels, supporting this idea." (PMID 29151835, 2017). "The levels of IL-4, IL-6, and IL-12 in children with moderate and severe asthma were close to the levels of those in normal control group after treatment (all P > 0.05)." (PMID 28328807, 2017). "IL-6 is also documented as one of the potential targets for the management and follow-up of chronic lung disease pathologies (e.g., asthma and COPD)." (PMID 28900313, 2017). "In asthma, IL-6 and TNFα positively correlated with the endogenous thrombin potential (β = 0.35 [95% CI, 0.28–0.42] and β = 0.15 [95% CI, 0.07–0.23], respectively) but not with CLT or platelet markers." (PMID 28429138, 2017). "Asthma is a Th-2 cell mediated disease, the elevated levels of IL-5 and IL-6 were seen in OVA-treated mice." (PMID 28293189, 2017).
asthma (continued). "In asthma, we demonstrated 62% higher plasma levels of IL-6 and 35% higher TNFα, also after adjustment for potential confounders (β = 0.43 [95% CI, 0.37–0.49] and β = 0.37 [95% CI, 0.31–0.43], respectively)." (PMID 28429138, 2017). "As previously reported, a significant increase in BrdU incorporation and IL-6 release was observed in both healthy subjects and patients with severe asthma after stimulation with FCS plus TGF-β (P < .001 vs unstimulated control ASMCs)." (PMID 27484035, 2017). "It is initially discovered that IL-4 and IL-6 levels were increased, whereas IL-12 level was decreased in PB of the asthma patients." (PMID 28328807, 2017). "Higher IL-6 in asthma subjects on antileukotriene medication was also documented after adjustment for asthma severity and other potential confounders (β = 0.17 [95% CI, 0.09–0.25])." (PMID 28429138, 2017). "Mononuclear phagocytes are the main source of IL-6; however, it is also produced by other inflammatory cells participating in asthma pathology, such as T and B lymphocytes, fibroblasts, and endothelial cells." (PMID 28429138, 2017). "The airway epithelium is a key contributor to the pathogenesis of asthma and has been shown to generate excess inflammatory and proinflammatory mediators, such as IL-6 and IL-8." (PMID 28116315, 2016). "In this study, maternal CES-D score was positively associated with IL-6 expression in children with asthma, and maternal JPSS score was positively related to IL-6 and IL-8 expressions among children with asthma and/or allergic rhinitis." (PMID 26819847, 2016). "Elevated IL-6, CRP, and soluble CD163 (macrophage activation marker) have been associated with reduced lung function (especially in severe asthma) and neutrophilic airway inflammation." (PMID 27212806, 2016). "IL-6 possesses wide effects on innate immune system and has been proposed to play an active role in asthma pathogenesis." (PMID 27212806, 2016). "Asthma susceptibility caused by this variation could be developed as an increase or reduction in NF-kB signaling that ultimately leads to an increase or reduction in the production of the pro-inflammatory mediators such as cytokines: interleukins IL-6 and IL-8." (PMID 27495363, 2016). "In conclusion, the most important finding from this study is that there are significant relationships between maternal psychological stress and IL-6 and IL-8 mRNA expressions in children with asthma and allergic rhinitis." (PMID 26819847, 2016). "IL-4 contributes to airway obstruction in asthma via the induction of mucus hypersecretion in mice and human cell lines, and increases the release of several pro-inflammatory cytokines such as IL-6, GM-CSF and eotaxin from human lung fibroblasts." (PMID 26758251, 2016). "Lungs of humans with asthma have a characteristic expression pattern of inflammatory cytokines, notable amongst those IL-4, IL-6, IL-13, IL-17A and TNF-α50, 51, 52, indicative of Th2 cells and Th17 cells." (PMID 27087690, 2016). "IL-6 and IL-8 are pro-inflammatory cytokines, and many studies have confirmed increased IL-6 and IL-8 expressions in patients with asthma and allergic rhinitis." (PMID 26819847, 2016). "A recent study on gene expression of blood CD4+ T cells from patients with depression and asthma showed that the main active pathways in depressive asthma are those related to acute phase protein signalling (such as IL-6 and CRP signalling)." (PMID 27212806, 2016). "The sputum IL-1RA levels were significantly correlated positively with lung function in patients with asthma and negatively with IL-6, which supports IL-1RA being anti-inflammatory in the airways." (PMID 25616863, 2015). "We determined the levels of 6 cytokines implicated in asthma, which can be divided by the response profiles Th1 (TNF-α and IL-6) and Th2 (IL-4, IL-13, IL-10, and IL-5)." (PMID 26101464, 2015).
asthma (continued). "Local and systemic levels of gal-3BP are elevated in asthma and inhibit Th2 cytokine transcription while promoting the production of IL-6." (PMID 25616863, 2015). "An immunoregulatory role for IL-6 in asthma and other pulmonary diseases where the lung epithelium is damaged has been highlighted." (PMID 26362930, 2015). "Airway smooth muscle (ASM) mass is increased in asthma, and ASM cells from patients with asthma are hyperproliferative and release more IL-6 and CXCL8." (PMID 25697361, 2015). "Various studies have shown that Th type 1 (Th1)-related cytokines (interleukin [IL]-12 and IFN-γ), Th type 2 (Th2)-related cytokines (IL-4, IL-5, and IL-13), and proinflammatory cytokines (IL-1β, IL-6, and TNF-α) are associated with asthma." (PMID 25658604, 2015). "IL-6 has been found to be upregulated in severe asthma, but its role in asthma is uncertain as it possesses both pro- and anti-inflammatory properties." (PMID 25883597, 2015). "While the role of IL-6 in allergic inflammation is less clear, it is a potent inflammatory cytokine, and has been shown to play a role in fungal-induced asthma." (PMID 26635806, 2015). "In our study, it has been found that BMMCs from asthma rat models had many differences compared to normal rats, including higher levels of β-hexosaminidase released and higher cytokines (IL-6, IL-13, TNF-α, histamine) secreted." (PMID 24995695, 2014). "In conclusion, using both bioinformatics and experimental tools we found a highly relevant potential role for microRNA dysregulation in the control of IL-6 and IL-8 expression in asthma." (PMID 25360780, 2014). "Air pollutants augment human airway inflammation through effects on IL-8 and IL-6, and IL-8 and IL-6 have important roles in neutrophilic airway inflammation in patients with asthma." (PMID 25386753, 2014). "The airway epithelium is a major contributor to asthma pathology and has been shown to produce an excess of inflammatory and pro-remodelling cytokines such as TGF-β, IL-6 and IL-8 as well as deficient amounts of anti-viral interferons." (PMID 25360780, 2014). "Specifically, smokers with asthma had raised IL-6 (p<0.001), IL-7 (p = 0.033) and IL-12 (p = 0.042)." (PMID 23951170, 2013). "The potential value of CRP, suPAR and IL-6 in the determination of asthma control was analyzed using ROC analysis." (PMID 23565268, 2013). "In severe asthma, the largest change (110-fold) is observed in Ifnγ expression followed by Il13, Il2, Il4, Il10, Il6, Il5, and Tnfα, respectively." (PMID 23781124, 2013). "We found that in the presence of 5% FCS human BSMC of asthma patients released a different complement of angiogenic regulators including angiogenin, IL-6, MCP-1 and importantly three CXCR2 ligands, namely ENA-78, GRO-α and IL-8." (PMID 24339939, 2013). "In mild asthma, Tbet expression was significantly correlated with Il2, Il4, Il5, Il6, Il13, and Tnfα expression." (PMID 23781124, 2013). "Remarkably, 15 out of 18 transcripts belong to the interaction network focused on the regulation of IL-6, a cytokine crucial in early asthma development." (PMID 23950928, 2013). "In severe asthma, an 8 and 33-times higher Il5 and Il6 expressions, respectively, was observed in allergen-sensitized and challenged mice but not in control, sensitized only, and challenged only mice." (PMID 23781124, 2013). "In the lung, for example, experimental evidence in mice suggests distinct roles for classic and trans-IL-6 signaling in the progression of airway inflammation and asthma." (PMID 23593036, 2013). "Specifically, IL-6 is elevated in individuals with asthma and is also regulated by ATF6 during activation of the UPR." (PMID 23369242, 2013). "Both PCT and IL-6 levels of patients with severe to critical asthma in the PCT group were higher than that of patients with mild to moderate asthma in the same group." (PMID 24341820, 2013). "IL-6 is involved in the pathogenesis of lung diseases such as asthma and chronic obstructive pulmonary disease." (PMID 23577829, 2013).